RCAN3 (regulator of calcineurin 3)
Description:
Inhibits calcineurin-dependent transcriptional responses by binding to the catalytic domain of calcineurin A. Could play a role during central nervous system development (By similarity).
Synonyms: MCIP3; DSCR1L2
Tractability: PROTAC: ubiquitination databases record sites on it; its protein half-life has been measured.
Gene: Protein-coding gene on chromosome 1 (24,502,340 to 24,541,040, forward strand). Ensembl gene ENSG00000117602.
Subcellular location (Human Protein Atlas): Nuclear speckles; Nucleoli fibrillar center
Pathways (Reactome):
Disease: SARS-CoV-1 activates/modulates innate immune responses
Gene Ontology:
Molecular function: phosphatase binding; protein binding; troponin I binding; calcium-dependent protein serine/threonine phosphatase regulator activity; RNA binding; nucleic acid binding
Biological process: anatomical structure morphogenesis; calcium-mediated signaling
Cellular component: cytoplasm; cytosol; nucleus
Genetic constraint (gnomAD): Loss-of-function variants: 21 observed, 23.16 expected, observed/expected ratio (o/e) 0.91, 90% interval 0.64 to 1.31. The upper end of that interval is the gene's LOEUF score, 1.31, which puts it in group 5 of 6, group 1 being the genes least tolerant of losing a copy. Missense variants: 240 observed, 288.14 expected, observed/expected ratio (o/e) 0.83, 90% interval 0.75 to 0.93. Synonymous variants: 114 observed, 108.23 expected, observed/expected ratio (o/e) 1.05, 90% interval 0.9 to 1.23.
Homologues: Orthologues: macaque RCAN3 (98% identical), guinea pig RCAN3 (93% identical), pig RCAN3 (90% identical), mouse Rcan3 (90% identical), rat Rcan3 (90% identical), chimpanzee RCAN3 (88% identical), tropical clawed frog rcan3 (79% identical), dog RCAN3 (74% identical), zebrafish rcan3 (73% identical), Drosophila melanogaster sra (37% identical), Caenorhabditis elegans rcan-1 (32% identical). Paralogues in human: RCAN2 (59% identical), RCAN1 (51% identical).
Diseases named in the same sentence as RCAN3 in open-access papers:
RCAN3 is named in the same sentence as 18 diseases in open-access papers, as found by Europe PMC text mining. Sharing a sentence is not in itself a finding about the gene and the disease. The quoted sentences say what the papers report.
breast carcinoma (2 papers, 2013 to 2024). "At present, RCAN3 can be used as a reliable marker for three cancer types (breast cancer, endometrial adenocarcinoma, and bladder cancer); however, its role in pan-cancer is less well-studied." (PMID 39219199, 2024). "Notably, RCAN3 and its derived peptide may impede breast cancer progression by inhibiting the CaN-NFATc signaling pathway." (PMID 39219199, 2024).
COVID-19 (2 papers, 2021 to 2025). A disease caused by infection with severe acute respiratory syndrome coronavirus 2. "Both, severe and mild COVID-19 in comparison to controls shared neutrophil-specific CD177 and HP expression among the most upregulated DEGs, as well as lymphocyte-associated genes such as ABLIM1, NELL2, RCAN3, RORC, BACH2, and KLRB1, among the downregulated genes." (PMID 33441124, 2021).
cardiac hypertrophy (1 paper, 2021). "Moreover, other molecules that are overexpressed in DS patients and are also related with cardiac hypertrophy could unveil similar questions: Are the elevated expression levels of DYRK1A, RCAN3 and DSCAM-AS1 involved in the cardiac hypertrophic response prevention observed in DS individuals?" (PMID 35126461, 2021).
cervical adenocarcinoma (1 paper, 2024). An adenocarcinoma arising from the cervical epithelium. "In later-stage cancer, RCAN3 expression in different types of cervical adenocarcinoma can be studied for differential diagnosis." (PMID 39219199, 2024). "For example, RCAN3 testing of samples after cervical cancer cytological screening may help to improve the screening rate of cervical adenocarcinoma." (PMID 39219199, 2024).
cervical cancer (1 paper, 2024). A primary or metastatic malignant neoplasm involving the cervix. "Therefore, this research aimed to determine the potential of RCAN3 as a diagnostic and prognostic biomarker in pan-cancer studies and as a molecular target for addressing cervical squamous cell carcinoma and endocervical adenocarcinoma cervical cancer (CESC)." (PMID 39219199, 2024). "RCAN3 expression is increased in cervical cancer tissues and correlates with adverse outcomes." (PMID 39219199, 2024). "Furthermore, RCAN3 knockdown inhibits the proliferation, invasion, and migration of cervical cancer cells." (PMID 39219199, 2024).
glioma (1 paper, 2024). A benign or malignant brain and spinal cord tumor that arises from glial cells (astrocytes, oligodendrocytes, ependymal cells). "Conversely, RCAN3 was downregulated in kidney renal clear cell carcinoma (KIRC) and lower-grade glioma (LGG)." (PMID 39219199, 2024).
myocardial infarction (1 paper, 2023). Gross necrosis of the myocardium, as a result of interruption of the blood supply to the area, as in coronary thrombosis. "No specific studies have examined the relationship between RCAN3 and CAD or smoking, except for a single study that demonstrated a negative association between DNA methylation and the risk of myocardial infarction." (PMID 37762221, 2023).
renal clear cell carcinoma (1 paper, 2024). "A decrease in RCAN3 expression in renal clear cell carcinoma and renal papillary cell carcinoma may be due to the presence of other compensatory mechanisms or alternative pathways that reduce RCAN3-dependent signal regulation." (PMID 39219199, 2024).
uveal melanoma (1 paper, 2024). A melanoma derived from melanocytes of the uveal tract. "The KM survival curve analysis revealed the impact of RCAN3 expression on patient prognosis (OS, DSS, and PFI) in three cancer types: CESC, LGG, and uveal melanoma (UVM)." (PMID 39219199, 2024).
cancer (4 papers, 2014 to 2024). A tumor composed of atypical neoplastic, often pleomorphic cells that invade other tissues. "RCAN3 displayed high accuracy in diagnosing and predicting cancers, and RCAN3 expression level was associated with the prognosis of certain cancers." (PMID 39219199, 2024). "RCAN3 demonstrated favorable diagnostic accuracy (AUC>0.7) in 20 cancer types and a notably high diagnostic accuracy (AUC>0.9) in 9 cancer types." (PMID 39219199, 2024). "Receiver operating characteristic (ROC) and Kaplan-Meier curves were employed to determine the diagnostic and prognostic value of RCAN3 in pan-cancer, respectively." (PMID 39219199, 2024). "Previous cancer studies have focused more on gene mutations, cell cycle regulation, and signaling pathways, and research on RCAN3 may provide a new perspective on how to prevent cancer progression by regulating calcium signaling pathways." (PMID 39219199, 2024). "In conclusion, the present research reveals that RCAN3 could serve as a diagnostic and prognostic biomarker and therapeutic target for pan-cancer." (PMID 39219199, 2024). "In general, RCAN3 can serve as a novel biomarker for the diagnosis and prognosis in pan-cancer, especially in CESC." (PMID 39219199, 2024). "The differences in RCAN3 expression in different types of cancer reflect the complexity and diversity of cancer biology." (PMID 39219199, 2024). "For a targeted treatment of cancer patients, it is possible to design small-molecule drugs targeting the functional domain of proteins, reducing RCAN3, and thus improving cancer prognosis." (PMID 39219199, 2024). "RCAN3 expression levels were assessed across pan-cancer data sets including various molecular and immune subtypes." (PMID 39219199, 2024). "RCAN3 expression varied not only in different cancer types but also in different molecular and immune subtypes of cancers." (PMID 39219199, 2024). "RCAN3 expression is elevated in most tumor types and often leads to a poor cancer prognosis." (PMID 39219199, 2024). "Additionally, RCAN3 expression significantly varied among immune subtypes in 6 cancer types and among molecular subtypes in 13 cancer types." (PMID 39219199, 2024). "Due to the central role of calcium signaling in cellular physiological and pathological processes, abnormal expression or dysfunction of RCAN3 may lead to changes in cellular behavior that contribute to the onset and development of cancer." (PMID 39219199, 2024). "In addition, RCAN3 test is expected to be used in combination with other clinical procedures and detection methods for the early screening and diagnosis of certain cancers." (PMID 39219199, 2024). "RCAN3 expression was increased across 25 cancer types and decreased in two cancer types." (PMID 39219199, 2024). "The upregulation of RCAN3 in other cancers may be related to enhanced cancer-related processes such as cell proliferation, migration, or inhibition of apoptosis." (PMID 39219199, 2024). "Therefore, a better understanding of RCAN3-related mechanisms could help in the development of new anti- treatment strategies, especially in cancer types that cannot be effectively treated." (PMID 39219199, 2024). "This suggests that RCAN3 may be a promising target for cancer screening and diagnosis." (PMID 39219199, 2024). "All the probes mapping to CpG islands associated with RCAN1 and RCAN3 (vertical bars above CpG islands) presented an unmethylated status in several normal and cancer human cell lines (data not shown), suggesting that these regions may be transcriptionally active." (PMID 24465593, 2014).
tumor (3 papers, 2021 to 2024). "In a similar manner, RCAN3 is implicated in the calcineurin–nuclear factor of activated T cells (NFAT) pathway-mediated immune response and also acts as a tumor suppressor." (PMID 33810219, 2021). "The present data suggests that RCAN3 may facilitate immune evasion by tumor cells, leading to reduced immune cell infiltration in the CESC tumor microenvironment, ultimately promoting CESC tumorigenesis and progression." (PMID 39219199, 2024).
RCAN3 also shares sentences with these, for which no sentence is quoted: Peripheral Artery Disease (2 papers); cervical squamous cell carcinoma (1); Pancreatic Cancer (1); renal papillary cell carcinoma (1); squamous cell carcinoma (1); uterine carcinosarcoma (1); uterine corpus endometrial carcinoma (1).